ERBB2 (erb-b2 receptor tyrosine kinase 2)
Diseases named in the same sentence as ERBB2 in open-access papers (continued):
Sharing a sentence is not in itself a finding about the gene and the disease.
mesenchymal tumors (5 papers, 2010 to 2025). "We analysed the expression level of ERBB2 within a series of 1725 mesenchymal tumours including 13 DSRCTs." (PMID 39921935, 2025).
pericardial effusion (5 papers, 2022 to 2025). Fluid collection within the pericardial sac, usually due to inflammation. "Among them, EGFR T790M, EGFR E746_A750delELREA, EGFR L861Q, KRAS G12C, EML4-ALK (exon 18: exon 20) fusion, EML4-ALK (exon 20: exon 20) fusion, and ERBB2 Y772_A755dupYVMA were detected in both pericardial effusion-cfDNA and pericardial effusion-sDNA." (PMID 35646096, 2022). "Among the 6 actionable alterations, EML4-ALK (exon 20: exon 20) fusion, ERBB2 Y772_A755dupYVMA and KRAS G12C showed a consistency of 100% between PE-cfDNA and pericardial effusion." (PMID 35646096, 2022).
renal failure (5 papers, 2022 to 2025). "The findings of our case-control study present substantial evidence that anti-ERBB2 therapies are associated with the occurrence of kidney failure as well as oligohydramnios among fetuses or newborns." (PMID 37883083, 2023).
rheumatoid arthritis (5 papers, 2018 to 2024). A chronic, systemic autoimmune disorder characterized by inflammation in the synovial membranes and articular surfaces. "As to ERBB2, it is highly expressed in rheumatoid arthritis synovial cells compared to controls." (PMID 31886203, 2019).
thyroid (5 papers, 2014 to 2025). "Most of the 16 thyroid-related genes, in addition to several cancer-related genes including AKT2, VEGFA, ERBB2, and CCND3, were positively correlated with TDS." (PMID 41353477, 2025).
type 1 diabetes (5 papers, 2012 to 2023). "Isolated heart perfusion model of global ischemia was used to study the effect of chronic inhibition or acute activation of EGFR/erbB2 signaling on cardiac function in a rat model of type-1 diabetes." (PMID 22720029, 2012). "Further, in a model of type 1 diabetes, the effect of acute activation or chronic inhibition of EGFR and ErbB2 signaling on heart function was also studied." (PMID 34408653, 2021).
uterine corpus endometrial carcinoma (5 papers, 2018 to 2025). A endometrial carcinoma (disease) that involves the body of uterus. "Another prognosis-related gene, ERBB2 was amplified in six cases (10.7%) of patients in a uterine corpus endometrial carcinoma dataset." (PMID 29459674, 2018).
apocrine tumors (4 papers, 2010 to 2023). "Thus, all five apocrine tumors for which we have RNA, DNA and immunohistochemical data show a specific genetic alteration in the ERBB2-PTEN-PIK3CA pathway." (PMID 20712882, 2010).
bone tumors (4 papers, 2013 to 2025). "As an important predictive factor for chemoresponse in many other cancers, Her-2/ERBB2 has been extensively studied in bone tumors, yet the role of Her-2 overexpression in the development of chemoresistance in OS and ES remains controversial and ambiguous." (PMID 24062983, 2013).
diffuse midline glioma (4 papers, 2022 to 2025). A diffuse glioma that arises from the midline structures of the central nervous system. "In a phase 1, clinical trial repetitive locoregional dosing of human erb-b2 receptor tyrosine kinase 2 (HER2)-specific CAR-T cells to children and young adults with recurrent/refractory CNS tumors, including diffuse midline glioma." (PMID 38349430, 2024).
endometrioid endometrial carcinoma (4 papers, 2020 to 2025). "The overexpression and amplification of HER-2/ERBB2 are notably more prevalent in serous endometrial carcinomas (ECs) compared to endometrioid endometrial carcinomas (EECs)." (PMID 40452892, 2025).
fibrosis (4 papers, 2021 to 2024). the formation of excess fibrous connective tissue in an organ or tissue in a reparative or reactive process.
gallbladder tumor (4 papers, 2019 to 2025). "Using mouse and cell culture models, a study found that gallbladder tumors or cancer cells harboring ERBB2/ERBB3 mutations showed an enhanced effect of anti-PD-1 treatment compared to WT43." (PMID 38502852, 2024). "We tested a series of five shRNA constructs in three gallbladder tumor cell lines expressing ERBB2 with wild type KRAS in OCUG1 cells, along with G415 and NOZ cells harboring the KRAS (G13D) and KRAS (G12V) mutant alleles, respectively." (PMID 30304546, 2019).
mastitis (4 papers, 2019 to 2025). Inflammation of breast tissue during lactation or postpartum due to an obstructed duct or infection. "Additionally, some of the highly connected genes belonging to this module have been found by others to be related to mastitis development, immune response or mammary gland development including FYN, CDH11, CAV1, F11R, ZEB1, ERBB2, and ERBB3." (PMID 32754201, 2020).
myelodysplastic syndrome (4 papers, 2016 to 2021). A clonal hematopoietic disorder characterized by dysplasia and ineffective hematopoiesis in one or more of the hematopoietic cell lines. "For instance, by clustering the curated signatures from genetic perturbation and diseases, we found multiple myelodysplastic syndrome (MDS) signatures from CD34+ cells that cluster with ERBB2 overexpression signatures from MCF10A cells." (PMID 30594974, 2019). "In the second cluster that we chose to highlight, multiple myelodysplastic syndrome (MDS) signatures from CD34+ cells (GSE4619, GSE19429) and ERBB2 overexpression signature from MCF10A cells (GSE14990) cluster together, suggesting that the up-regulation of ERBB2 may have a role in MDS." (PMID 27667448, 2016).
neurofibroma (4 papers, 2023 to 2025). An intraneural or extraneural neoplasm arising from nerve tissues and neural sheaths. "In addition, targeted therapy of EGFR/ErbB2 inhibits ErbB2 phosphorylation and Survivin upregulation, as well as downstream ERK1/2 and AKT activation, thereby reducing neurofibroma cell proliferation, which is consistent with our results of Survivin downregulation." (PMID 39346787, 2024).
oligohydramnios (4 papers, 2020 to 2025). A lower than normal quantity of amniotic fluid in the amniotic sac as compared to normal values. "Exposure to anti-ERBB2 agents during pregnancy (n = 328) was significantly associated with an overreporting of oligohydramnios, congenital respiratory tract disorders, and neonatal kidney failure relative to other anticancer drugs (n = 3230)." (PMID 37883083, 2023). "We found that specific adverse outcomes (oligohydramnios, congenital respiratory disorders, and neonatal kidney failure) were more frequently reported for anti-ERBB2 treatments than for other anticancer drugs." (PMID 37883083, 2023). "The 5 complications most frequently reported in the anti-ERBB2 drug group were oligohydramnios (78 [23.8%]), preterm birth (57 [17.4%]), intrauterine growth restriction (32 [9.8%]), neonatal respiratory disorder (24 [7.3%]), and spontaneous abortion 24 [7.3%])." (PMID 37883083, 2023). "Whenever delaying anti-ERBB2 therapy is not possible, continuous monitoring for oligohydramnios becomes imperative, and anti-ERBB2 drugs should be withdrawn in the case of oligohydramnios." (PMID 37883083, 2023).
Parkinson disease (4 papers, 2016 to 2022). A progressive degenerative disorder of the central nervous system characterized by loss of dopamine producing neurons in the substantia nigra and the presence of Lewy bodies in the substantia nigra and locus coeruleus. "Mutations of ERBB2 could provide key answers into its role in Alzheimer’s and Parkinson’s diseases." (PMID 34379632, 2021).
preeclampsia (4 papers, 2017 to 2025). Preeclampsia is a hypertensive disorder of pregnancy that is characterized by new-onset hypertension with proteinuria presenting after 20 weeks of gestation, and depending on mild or severe forms may initially present with severe headache, visual disturbances, and hyperreflexia. "Given its role in cell growth and differentiation, ERBB2 may indirectly influence placental development and function, which are critical factors in the pathogenesis of preeclampsia." (PMID 41220585, 2025). "However, there is limited direct research on the relationship between the ERBB2 gene and preeclampsia." (PMID 41220585, 2025). "The most relevant targets for preeclampsia were: AR, VDR, SLC6A2, NOS3 and CHRM4, while ABCG2, ERBB2, CES1 and REN led to the most relevant off-targets." (PMID 33546161, 2021).
small bowel cancer (4 papers, 2019 to 2024). "A recent study on genomic variants demonstrated that CDKN2A/B and ERBB2/HER2 variants are more enriched in duodenal cancer than in small-bowel cancer and duodenal cancer overall tends to have lower TMB." (PMID 34014970, 2021). "Few publications describe the importance of ERBB2 mutations in small bowel carcinomas." (PMID 30717682, 2019). "Our results underscore, in particular, the relevance of potentially treatable molecular alterations (like ERBB2, BRCA and MSI) in small bowel carcinomas." (PMID 30717682, 2019).
squamous non-small cell lung cancer (4 papers, 2019 to 2023). "For non-small-cell lung squamous cell carcinoma (designated Lung_Nsclc_SCC) and gastric (designated Stomach) cancer cell lines, ErbB2 expression was significantly associated with sensitivity to 44% of drugs targeting ErbBs." (PMID 37508418, 2023).
Vestibular schwannoma (4 papers, 2014 to 2021). A vestibular schwannoma (also known as acoustic neuroma, acoustic neurinoma, or acoustic neurilemoma) is a benign, usually slow-growing tumor that develops from the VIIIth cranial nerve supplying the inner ear. "The importance of ErbB2 in NF2-associated tumors is also highlighted by recent research showing that lapatinib inhibits vestibular schwannoma growth." (PMID 24817309, 2014). "Clinical analysis has shown that vestibular schwannomas overexpress ErbB2/3 and that EGFR and its ligand are up-regulated in the majority of NF2-related vestibular schwannomas." (PMID 24393766, 2014). "Lapatinib, which targets EGFR and ErbB-2, is being examined in both a phase 0 study treating vestibular schwannomas (NCT00863122) and a phase II (NCT00973739) trial for its effectiveness in all NF2 related tumor types." (PMID 24393766, 2014).
adenocarcinoma in situ (3 papers, 2017 to 2024). A lesion in which the normally situated glands are partially or completely replaced by atypical cells with malignant characteristics. "What's more, we found that the mutation of EGFR increased significantly from adenocarcinomas in situ (AIS, 21.4%) to microinvasive adenocarcinomas (MIA, 52.4%) and invasive adenocarcinomas (IA, 61.1%), while the mutation of ERBB2 dropped markedly from AIS (21.4%) to MIA (9.5%) and IA (4.1%)." (PMID 38496837, 2024).
benign prostatic hyperplasia (3 papers, 2010 to 2024). A non-cancerous nodular enlargement of the prostate gland. "FISH analysis of 371 tissue samples that included benign prostatic hyperplasia (BPH), primary, locally recurrent, and metastatic PC showed no ERBB2 amplifications in any PC samples irrespective of disease stage." (PMID 39409883, 2024).
bile duct cancer (3 papers, 2022 to 2024). "Among the bile duct carcinoma patients who performed next-generation sequencing (NGS) testing, 5.4% report gene alterations involving HER2, of which 2.4% amplifications, 2.3% ERBB2 mutations, and 0.4% with mutations and amplifications present simultaneously." (PMID 38846220, 2024).
brainstem glioma (3 papers, 2023 to 2025). "Convection-enhanced locoregional delivery of nano-encapsulated genes generates ErbB2/Her2-specific CAR-macrophages for brainstem glioma immunotherapy." (PMID 40223940, 2025). "Our technology therefore constitutes a practical antitumor immunotherapy for brainstem glioma and may be broadly applicable for patients suffering from other ErbB2-positive solid malignancies." (PMID 36805678, 2023). "Our work demonstrates a practical antitumor immunotherapy for brainstem gliomas (BSGs) that may be broadly applicable for patients suffering from other ErbB2-positive solid malignancies." (PMID 36805678, 2023).
colon adenoma (3 papers, 2017 to 2020). An adenoma that arises from the colon.
Crohn disease (3 papers, 2022 to 2024). A gastrointestinal disorder characterized by chronic inflammation involving all layers of the intestinal wall, noncaseating granulomas affecting the intestinal wall and regional lymph nodes, and transmural fibrosis. "In addition, we identified, albeit rarely, potentially targetable alterations, such as IDH1 or ERBB2 mutations or MMRd/MSI, in such aggressive cancers, most of which (80%) were associated with Crohn disease." (PMID 36812376, 2023).
dengue (3 papers, 2020 to 2025). "We observed that EPHB3, ERBB2, FGFR2, IGF1R, and RET are upstream regulators both of kinases shown to be important in previous dengue research and of kinases predicted by KiR." (PMID 38585651, 2024). "Thus, the activity of ERBB2 and IGF1R during DENV infection should be further investigated to understand their utility as dual targets of dengue therapeutics." (PMID 38585651, 2024).
diabetic cardiomyopathy (3 papers, 2022 to 2025). Diabetic cardiomyopathy is a disorder of the heart muscle in people with diabetes. "The expression of cardiac NRG1 and the phosphorylation of ErbB2 and ErbB4 are reduced in in vitro (cellular) and in vivo (rat models) of diabetic cardiomyopathy." (PMID 35370955, 2022).
duodenal adenocarcinoma (3 papers, 2010 to 2025). A carcinoma that arises from glandular epithelial cells of the duodenum. "Another study of 83 patients confirmed these findings, reporting increased ERBB2 mutation rate in duodenal adenocarcinomas (15.8%) compared to jejunal and ileal adenocarcinomas (2.2%)." (PMID 35267592, 2022). "Amongst SBA tumors, those identified as duodenal adenocarcinomas harbor significantly increased ERBB2/HER2 alteration frequency (p < 0.01) compared to other SBA tumors." (PMID 35267592, 2022). "However, when comparing duodenal adenocarcinomas to cancers of other small bowel sites, both CDKN2A (18% vs. 10%) and ERBB2 (13% vs. 4%) alteration rates were higher in duodenal adenocarcinomas." (PMID 35267592, 2022).
follicular thyroid cancer (3 papers, 2020 to 2022). "The human epidermal growth factor receptor 2 (HER2) gene (ERBB2) overexpression was discovered in follicular thyroid cancer (FTC) (44%), PTC (18%), and some ATC." (PMID 36157447, 2022). "First, the role of ERBB2 in follicular thyroid cancer, poorly differentiated thyroid cancer, and anaplastic thyroid cancer could not be investigated because those pathological types or endpoint information were lacking in online databases." (PMID 36437939, 2022).
hereditary cancer (3 papers, 2008 to 2025). Malignant neoplasms occurring in families at a rate greater than that expected by chance and caused by germline mutations in a specific gene. "De novo FAP with double germline mutations in APC and BRCA2, along with somatic ERBB2 mutations, is exceptionally rare among hereditary cancer cases." (PMID 39985003, 2025).
hilar cholangiocarcinoma (3 papers, 2009 to 2026). A cholangiocarcinoma that arises from the junction, or adjacent to the junction, of the right and left hepatic ducts. "However, the efficacy of ERBB2 mutated hilar cholangiocarcinoma (hCCA) against ERBB2 is rarely reported." (PMID 35875132, 2022). "This study has shown the potential of trastuzumab combined with capecitabine as an effective treatment for hilar cholangiocarcinoma complicated by liver metastases harboring ERBB2 alterations." (PMID 35875132, 2022).
insomnia (3 papers, 2021 to 2025). A sleep disorder characterized by difficulty in falling asleep and/or remaining asleep. "These high-degree protein targets may be the key targets such as neurotrophic receptor tyrosine kinase 1, nuclear receptor subfamily 3 group C member 1, cyclin D1, erb-B2 receptor tyrosine kinase 2, and account for the essential therapeutic effects of CWT on insomnia." (PMID 36110515, 2022).
ischemia (3 papers, 2012 to 2021). A hypoperfusion of the BLOOD through an organ or tissue caused by a PATHOLOGIC CONSTRICTION or obstruction of its BLOOD VESSELS, or an absence of BLOOD CIRCULATION. "In this study our initial goal was to determine whether the inhibition or activation of erbB2 and EGFR signaling was able to aid or exacerbate recovery of cardiac function following global ischemia in isolated hearts from normal or streptozotocin-induced diabetic rats." (PMID 22720029, 2012).
left ventricular dilation (3 papers, 2017 to 2022). "rhNRG1 treatment induced systemic activation of ErbB2 and ErbB4 receptors in both heart and kidneys and prevented left ventricular dilatation, improved left ventricular contractile function, and reduced atherosclerotic plaque size." (PMID 36120374, 2022).
leukocytosis (3 papers, 2022 to 2025). "Moreover, while we observed that markers such as EPCAM and ERBB2 were downregulated in CRC, further research is required to clarify the impact of inflammatory responses, such as leukocytosis, on the detectability of circulating RNA in patients with CRC." (PMID 40003943, 2025).
non-alcoholic steatohepatitis (3 papers, 2020 to 2025). "By contrast, in non-alcoholic steatohepatitis (NASH), we detected a significantly lower ErbB2 positivity." (PMID 32591879, 2021). "Strikingly, in non-alcoholic steatohepatitis (NASH), ErbB2 expression was low (score 1) to negative and reached in no case a medium (score 2) to strong (score 3) expression level." (PMID 32591879, 2021).
ovarian serous tumor (3 papers, 2018 to 2020). A benign, borderline, or malignant epithelial tumor of the ovary characterized by the presence of neoplastic epithelial cells that, in well differentiated tumors, resemble the epithelial cells of the fallopian tube and, in poorly differentiated tumors, show anaplastic features. "Moreover, a previous study indicated that the expression of ErbB2 was positively correlated with the malignant potential of serous ovarian neoplasms." (PMID 29482638, 2018).
penile cancer (3 papers, 2011 to 2025). A primary or metastatic malignant neoplasm that affects the penis. "Moreover, ERBB2 mutations have also been described in penile cancer and have been associated with aggressive disease." (PMID 40665654, 2025).
primary immunodeficiency (3 papers, 2018 to 2022). "GSEA analysis adds more insight into the 23 ERBB2-related DEGs and primary immunodeficiency signaling pathway, showing that ERBB2-related DEGs associated with primary immunodeficiency were mainly down-regulated ERBB2-related DEGs, such as CD79A, CD19, CD3D, CD3E, CD8A, and CD4." (PMID 36437939, 2022).
small bowel adenocarcinoma (3 papers, 2015 to 2021). "ERBB2 mutations and/or amplifications have been detected in up to 23% of small bowel adenocarcinomas and they are associated with duodenal location and microsatellite instability." (PMID 33922305, 2021). "Interestingly ERBB2 inhibitors have been found to display anti-cancer activity in small bowel adenocarcinomas, both in vitro and in vivo." (PMID 33922305, 2021).
-dependent (2 papers, 2023 to 2025). "Drugs aimed at ERBB2, FCGR3A, and FLT3 are primarily used in treating various cancers and benign tumors, while ALDH2 is targeted in therapies for a range of systemic diseases, notably cancer and substance dependence." (PMID 40868097, 2025).